MMP8 (matrix metallopeptidase 8)
Diseases named in the same sentence as MMP8 in open-access papers (continued):
Sharing a sentence is not in itself a finding about the gene and the disease.
periodontitis (continued). "A research study investigated IL-1β, IL-6, MMP-8, and IL-10 levels in healthy as well as periodontitis patients and found that IL-1β and IL-6 concentrations were significantly higher in periodontitis patients." (PMID 36289921, 2022). "It is suggested that salivary MMP‐8 can distinguish between periodontitis and healthy individuals with an accuracy of about 80%." (PMID 35769040, 2022). "Both MMP-8 and MMP-9 are extremely valuable diagnostic tools in treating periodontitis, and future studies and healthcare policies should focus on implementing more accessible methods of chairside testing in order to reduce the prevalence of this disease." (PMID 35163727, 2022). "Periodontal bacteria stimulate immune cells to release MMP8 into the bloodstream, and studies have shown that serum MMP8 levels are higher in patients with generalized and invasive periodontitis." (PMID 34211440, 2021). "The major cellular source of MMP-8 are polymorphonuclear neutrophils (PMN) and increased production levels of aMMP-8 signify the progression of gingivitis into periodontitis, with associated soft tissue destruction." (PMID 34353321, 2021). "This study aimed to assess the origin of MMP-8 and Lactoferrin in periodontitis patients and to identify the degree to which conventional clinical parameters correlate with their presence." (PMID 34353321, 2021). "The periodontitis group showed significantly higher levels of IL-1β, MMP-8, ICTP, and Pg compared to the healthy group and higher levels of IL-1β, ICTP, and Pg compared to the gingivitis group." (PMID 34001101, 2021). "Even when total and active MMP-8 levels were raised in periodontitis, compared to gingivitis and healthy sites in the literature, active MMP-8, detected by IFMA, was a better predictor of periodontal status in previous works." (PMID 34441437, 2021). "As expected, we found significantly higher levels of MMP-8 in periodontitis versus healthy subjects and severe than mild sites, measured both by IFMA and ELISA methods." (PMID 34441437, 2021). "When comparing MMP-8 forms between different sites affected by periodontitis, it was observed that (a) MMP-8 was greater in severe (458.84 (552.51 ng/mL)) than mild sites (218.57 (399.92 ng/mL)), with statistically significant differences (p < 0.001)." (PMID 34441437, 2021). "In our study, MMP-8 was detected in significantly higher levels within the diseased groups (gingivitis and periodontitis) compared to the healthy group." (PMID 34001101, 2021). "This study aimed to evaluate the applicability of active matrix metalloproteinase (a) MMP-8 immunotest versus total (t) MMP-8 ELISA for the quantitative real-time diagnosis and assessment of site severity of periodontitis." (PMID 34441437, 2021). "This can be explained, at least in part, due to the fact that the more MMP-8 is converted to its active form, the more clinically active, progressive or up-graded periodontitis is." (PMID 34441437, 2021). "The combination of IL-1β, ICTP, and Pg can be used to discriminate periodontitis subjects from healthy subjects and gingivitis subjects, and the combination of IL-1β and MMP-8 can be used to discriminate gingivitis subjects from healthy subjects." (PMID 34001101, 2021). "MMP-8 appears to be the most promising host derived enzyme as a biomarker for the progression of periodontitis vs. stable periodontitis." (PMID 33916672, 2021). "Neutrophil collagenase, also known as matrix metalloproteinase-8 (MMP-8) is one of the most representative enzyme involved in the breakdown of the extracellular matrix in Periodontitis." (PMID 33916672, 2021). "After peri-implantitis treatment, a decrease in active MMP-8 in the peri-implant sulcus fluid was found in periodontitis patients." (PMID 34054959, 2021). "MMP-8 is one of the hopeful biomarkers for pulp inflammation diagnosis, however, MMP-8 is also detected in GCF from chronic periodontitis patients." (PMID 38947881, 2021).
periodontitis (continued). "IFMA also reported a 63.1% of MMP-8 reduction after periodontal therapy of periodontitis sites, while MMP-8 post-therapy changes recorded by ELISA were not significantly different." (PMID 34441437, 2021). "Matrix metalloproteinase (MMP-8) plays a crucial role in the pathogenesis of periodontitis and is also a possible biomarker candidate in peri-implantitis." (PMID 34054959, 2021). "Previous studies showed that MMP-8 levels are closely related with the turnover and destruction of periodontal tissues, which is one of the indicators for the diagnosis of periodontitis." (PMID 34592963, 2021). "In fact, some authors considered MMP-8 as the main collagenase in periodontitis, since 90% to 95% of collagenolytic activity in gingival crevicular fluid and saliva is actually derived from higher levels of MMP-8 compared to healthy individuals." (PMID 34353321, 2021). "Saliva from the periodontitis subjects had significantly higher mean levels of MMP-8 (p = 0.03) and MMP-9 (p = 0.03) than saliva from the healthy subjects." (PMID 35048079, 2021). "A recent systematic review reported that the interleukin-1 beta, interleukin-6, macrophage inflammatory protein-1 alpha, and matrix metalloproteinase-8 (MMP-8) levels are potential salivary biomarkers for the diagnosis of periodontitis." (PMID 34415974, 2021). "The combination of IL-6 and MMP-8 showed, for periodontitis vs. healthy gingiva, a high sensitivity of 94% and a specificity of 100%." (PMID 33916672, 2021). "This study aimed to compare the effect of subgingivally delivered propolis extract (a resin produced by honey bees) with chlorhexidine (CHX) mouthwash on clinical parameters and salivary levels of matrix metalloproteinase 8 (MMP-8) in periodontitis patients." (PMID 35919679, 2021). "Salivary interleukin (IL)-1β, matrix metalloproteinase (MMP)-8, pyridinoline cross-linked carboxyterminal telopeptide of type I collagen (ICTP) and Porphyromonas gingivalis (Pg) are related to periodontitis." (PMID 34001101, 2021). "Although BOP and MMP-8 levels have been shown to allow distinction between a healthy periodontal status and gingivitis or periodontitis cases, other studies have shown conflicting or contrary results." (PMID 33567492, 2021). "Matrix metalloproteinase-8 (MMP-8) levels can effectively diagnose gingivitis, which is an early inflammatory prerequisite state to periodontitis." (PMID 33668185, 2021). "Matrix metalloproteinase‐8 (MMP‐8), MMP‐9, and tumor necrosis factor alpha (TNF‐α) levels were higher in periodontitis and in RA and MMP‐8 levels increased with the severity of periodontitis." (PMID 33954982, 2021). "Multiple studies have suggested MMP-8 and IL-1β, various others have found that MMP-8 is the most reliable indicator present persistently in periodontitis." (PMID 33668185, 2021). "IFMA was more effective in the detection of periodontitis, whereas MMP-8 recorded by ELISA was scarcely detected in GCF from healthy sites." (PMID 34441437, 2021). "This study aimed to evaluate the diagnostic performance of active (a) MMP-8 immunotest versus total (t) MMP-8 ELISA for quantitative real-time diagnosis and assessment of periodontitis severity at the site level." (PMID 34441437, 2021). "Since that time, a number of potential targets have been investigated for utility in the detection and monitoring of periodontitis, such as MMP-8, MMP-13, MMP-14, myeloperoxidase and azurocidin." (PMID 33291429, 2020). "In fact, it has been specifically reported that the concentration of MMP8 in the GCF of patients with periodontitis versus periodontally-healthy controls was 428.6 (±332.4) versus 95.2 ng/mL (±70.2), respectively." (PMID 33255937, 2020). "This study aimed to evaluate the effects of local application of vitamin C in tissue levels of AGE, IL-6, 8-OHdG, and MMP-8, in serum levels of CTX and periodontal attachment loss in diabetic rats with induced periodontitis." (PMID 33263670, 2020).
periodontitis (continued). "According to several studies, the association between periodontitis and high levels of IL-1β, TNF-α, and MMP-8 in the GCF is well established." (PMID 32064567, 2020). "Biomarkers that decreased after scaling and root planning (SRP) and oral hygiene instruction (OHI) in periodontitis patients were IL-1β, MMP-8, MMP-9, prostaglandin E2 (PGE2), and TIMP-2." (PMID 33383828, 2020). "It has been reported that MMP-8 levels in both gingival tissue and serum increase in diabetes and periodontitis." (PMID 33263670, 2020). "Previous studies have found that individual patients diagnosed with periodontitis showed significant elevations of the MMP-8 concentration compared to healthy groups." (PMID 32503210, 2020). "Non-surgical periodontal treatment adjuvated by the use of ozonated oil led to a significant and faster reduction in saliva MMP-8 concentrations in patients with periodontitis." (PMID 32932898, 2020). "The biomarkers that decreased after SRP and OHI in periodontitis patients were IL-1β, MMP-8, MMP-9, PGE2, and TIMP-2." (PMID 33383828, 2020). "Notwithstanding, it is widely known that MMP8 is one of the main proteases involved in the destruction of the alveolar bone in periodontitis, and it is a known collagenase that breaks down the type I collagen." (PMID 33255937, 2020). "It has been reported that a rapid chair-side test of MMP8 in gingival crevicular fluid can be used to distinguish periodontitis from gingivitis and healthy gingiva." (PMID 33046027, 2020). "A cohort study that included seven biomarkers showed that IL-1β, IL-6 and MMP-8 combination was the most sensitive and specific for discriminating health from periodontitis." (PMID 33081038, 2020). "Combining clinical measures, pathogen levels, and cytokines like interleukin (IL)-1β, osteoprotegerin (OPG) and matrix metalloproteinases (MMP)-8 can provide up to 74% sensitivity for predicting periodontitis progression." (PMID 33343358, 2020). "Pathologically involved peri-implant sites showed a similar pattern of elevated MMP8 level in PISF to that observed in periodontitis sites, with a similar cellular source being mainly derived from inflammatory cells, particularly PMNs." (PMID 33081038, 2020). "The increase was considered to reflect the increased leakage of all types of MMP-8 according to the severity of periodontitis." (PMID 33066545, 2020). "MMP-8 and IL-1 β are the most researched biomarkers in related researches, both showing clinically fair effectiveness for the diagnosis of periodontitis." (PMID 33383828, 2020). "MMP-8 levels in GCF have demonstrated a high potential to identify individuals with periodontitis and reflect its severity, while OPG levels have been associated with the quantity and severity of periodontal bone destruction." (PMID 33143325, 2020). "In health, MMP8 in oral fluids is mainly in its latent form, while the expression of the activated form increases in response to periodontal/peri-implant diseases." (PMID 33081038, 2020). "In this study, we demonstrated that MMP-8, TRAP-5, and OPG in GCF exert a high diagnostic performance in periodontitis, discriminating between incipient/early and more advanced levels of the disease." (PMID 33143325, 2020). "After adjustment by periodontitis, the significant differences of MMP8 levels between the groups was maintained (p = 0.042)." (PMID 33255937, 2020). "We assessed the diagnostic potential of matrix metalloproteinase-8 (MMP-8), tartrate-resistant acid phosphatase-5 (TRAP-5), and osteoprotegerin (OPG) to discriminate between healthy patients’, mild and severe periodontitis sites." (PMID 33143325, 2020). "During disease, MMP8 is one of the major collagenolytic enzymes highly involved in the destruction of periodontal/peri-implant tissue and progression of periodontitis/peri-implantitis." (PMID 33081038, 2020).
periodontitis (continued). "On the population level, as MMP8 is associated with the severity of periodontal diseases, the MMP8 chairside test can be very useful to identify early detection of periodontitis in epidemiological investigations." (PMID 32481582, 2020). "It has been shown that MMP-8 and -9 are the predominant MMPs and the most important enzymes that control the pathogenesis of periodontitis." (PMID 33391628, 2020). "GCF MMP-8 activation was found to be the highest in chronic periodontitis patients compared with healthy subjects and gingivitis patients." (PMID 32650590, 2020). "MMP8 overexpression is supposed to be the single most helpful biomarker in the diagnosis of periodontitis." (PMID 33255937, 2020). "Among the tested biomarkers, salivary and oral rinse levels of MMP-8 are shown to be effective in distinguishing periodontitis patients from periodontally healthy individuals." (PMID 32143418, 2020). "MMP-8 had the overall best performance in regression models and Receiver Operating Characteristic (ROC) curves, with high discrimination of healthy from periodontitis sites (area under the curve (AUC) = 0.901)." (PMID 33143325, 2020). "When comparing chronic periodontitis patients with gingivitis patients and healthy control subjects, higher levels of MMP-8 in saliva and higher MMP-9 levels in gingival crevicular fluid (GCF) were detected." (PMID 32650590, 2020). "The MMP-8/aMMP-8 is a promising candidate biomarker to diagnose, predict, grade periodontitis/peri-implantitis and monitor their treatments." (PMID 32764436, 2020). "The levels of salivary biomarkers, including IL-1, IL-6, and MMP-8, are reported to be significantly increased in patients with periodontitis in comparison with healthy controls." (PMID 33383828, 2020). "The ELISA and biosensor assays both recorded a significant reduction in salivary MMP-8 after periodontitis treatment in the group as a whole." (PMID 31363141, 2019). "According to several studies, the progression of periodontitis is reflected as an excessive elevation and activation of MMP-8 in oral fluids." (PMID 30909530, 2019). "Activated matrix metalloproteinase-8 (MMP-8) is a major destructive collagenase in periodontitis but, also, a potential biomarker for initial periodontitis/subclinical periodontitis/pre-periodontitis as well as periodontitis." (PMID 30909530, 2019). "Salivary MMP-8 measurements using both analytical methods correlated similarly with clinical measures of periodontitis taken at the beginning of study." (PMID 31363141, 2019). "Results indicated that peri-implantitis PICF contained higher active MMP-8 levels than GCF from similar deep chronic periodontitis sites of natural teeth." (PMID 31817894, 2019). "We then assayed MMP-8 in saliva taken from a sub-group (n = 20) of periodontitis patients using the biosensor assay and recorded a similarly significant reduction in posttreatment MMP-8 levels in the group as a whole (P = 0.026)." (PMID 31363141, 2019). "Numerous studies confirm that MMP-8 in oral biofluids (and in particular gingival crevicular fluid, GCF) is quantitatively associated with clinical measures of periodontitis both cross-sectionally and longitudinally during treatment." (PMID 31363141, 2019). "Analysis using both the ELISA and the new MMP8 biosensor indicated that the levels of salivary MMP-8 were significantly different (P < 0.001) between healthy volunteers, patients with untreated gingivitis and patients with untreated periodontitis." (PMID 31363141, 2019). "We did identify some 7 periodontitis patients with MMP-8 levels >2000 pg/ml which are outwith the range of data we recorded for other patients but within the range recorded in a meta analysis of other studies of salivary MMP-8 levels." (PMID 31363141, 2019). "For example, expression of MMP8 is increased in gingivitis as well as periodontitis and MMP8 has been shown to suppress neuroinflammation and inflammation in osteoarthritis." (PMID 31514474, 2019).
periodontitis (continued). "Similar to what was found in periodontitis, there is moderate evidence in the literature showing high MMP-8 levels in PI compared to healthy implant sites." (PMID 31817894, 2019). "Other research recording the utility of salivary MMP-8 assays in diagnosis of periodontitis has likewise employed assays using antibodies to total MMP-8 in ELISA assays." (PMID 31363141, 2019). "A study testing accuracy of the cumulative risk score calculated (CRS) from three salivary biomarkers (i.e., P. gingivalis, IL-1β, and MMP-8) was more accurate in the diagnosis of advanced periodontitis than any of the markers alone." (PMID 30305812, 2018). "It was found that the MMP-8/TIMP molar ratio and the combination of two biomarkers, MMP-8 and pyridinoline cross-linked carboxyterminal telopeptide of type I collagen (ICTP), were significantly higher in detecting periodontitis compared to MMP-8 test alone." (PMID 30305812, 2018). "In patients with mild periodontitis, moderate periodontitis, and severe periodontitis, the MMP-8 levels in GCF were 7.40 ± 9.07 ng/mL, 12.43 ± 10.06 ng/mL, and 13.17 ± 16.43 ng/mL, respectively." (PMID 28757684, 2017). "These are two different chair-side mouth rinse and PISF tests based on an active MMP-8 (aMMP-8) immunoassay for measuring the inflammatory burden of periodontitis and peri-implantitis." (PMID 28117682, 2017). "Below we summarize the observations in three different protease knockout mouse models, those with the following genes knocked out: Mmp-8, Cathepsin K, and plasminogen in periodontitis mouse models." (PMID 29163477, 2017). "Ex vivo evidence from progressive chronic periodontitis in humans supports a role for MPO in direct activation of latent MMP-8 and MMP-9, and the inactivation of TIMP-1." (PMID 28218665, 2017). "The results of this study have indicated that the levels of MMP-8 in the GCF from patients with various severity of periodontitis were significantly higher than in patients with healthy periodontium." (PMID 28757684, 2017). "In periodontitis, pro-inflammatory cytokines can stimulate gingival fibroblasts to secrete MMP-8, thereby enhancing ECM and basement membrane breakdown, which is one of the possible mechanisms causing periodontitis." (PMID 28423488, 2017). "MMP-8 has aroused interest for it has been found in various inflammatory diseases, such as periodontitis, bronchitis, asthma and arthritis." (PMID 28403357, 2017). "Some authors have indicated that in GCF obtained from patients with advanced or aggressive periodontitis, MMP-8 levels are significantly higher than in patients with a healthy periodontium." (PMID 28757684, 2017). "The aMMP-8 chairside test is performed on participants to identify individuals with elevated saliva MMP-8 in periodontitis patients." (PMID 28117682, 2017). "In a study by Kuula and coworkers, the role of MMP-8 in periodontitis was investigated using an Mmp-8 knockout mouse model infected with P. gingivalis." (PMID 29163477, 2017). "A meta-analysis involving in excess of 6000 individuals established that MMP-9-753 C/T polymorphism reduced the risk of chronic periodontitis, while MMP-3-1171 5A/6A and MMP-8-799 C/T polymorphisms increased the risk of chronic periodontitis." (PMID 28218665, 2017). "In fact, MMP-8 (or collagenase 2) currently represents one of the most promising biomarkers for periodontitis in oral fluids." (PMID 28218665, 2017). "Inflammatory biomarkers, such as IL-1β, IL-6, and IL-8, MMP-8, TIMP-1 and TNF-α associated with oral diseases: dental caries, gingivitis and periodontitis have been detected in saliva." (PMID 28117682, 2017). "In our previous studies, we have documented that scaling and root planing (SRP) in patients with chronic periodontitis resulted in a significant decrease in MMP-8 concentration in GCF." (PMID 28757684, 2017). "MMP‐8 (neutrophil collagenase) is the most abundant and important biomarker in periodontitis reflecting the initiation and progression of the disease." (PMID 29744169, 2016).